LEP (leptin)
Diseases named in the same sentence as LEP in open-access papers (continued):
Sharing a sentence is not in itself a finding about the gene and the disease.
malnutrition (continued). "In this single-center cohort study, authors aimed to investigate which of the chosen inflammatory markers (leptin, IL-18, IL-6, IL-1α, TNFα) may contribute to malnutrition and its consequences the most, and further reflected upon possible interventions, based on the most up-to-date literature." (PMID 36558477, 2022). "Results in a clinical investigation, in order to clarify the relationship between anthropometric data and concentrations of serum leptin in the catch-up growth procedure, showed that increasing leptin concentrations might trigger catch-up growth in children recovering from malnutrition." (PMID 34925230, 2021). "The late stages of CKD are related to protein–energy wasting (reduced body protein and fat mass, and usually reduced protein and energy intake), and since leptin inhibits appetite, it may contribute to a further deterioration of nutritional status or even to malnutrition." (PMID 32182671, 2020). "However, the existing literature on leptin levels during malnutrition is mixed." (PMID 32525953, 2020). "Thus, parasites may induce the malnutrition state, which is the hall mark of low systemic leptin levels and disturb the host immunity." (PMID 32824322, 2020). "Importantly, leptin has a crucial role in mediating innate and adaptive immune response which are significantly affected by nutritional status and play a vital role in the immune adaptation in both malnutrition and infection." (PMID 30534129, 2018). "Finally, the high leptin to fat mass ratio observed in people born with a low weight could be a sequel of malnutrition during foetal life." (PMID 27141948, 2016). "Serum leptin levels are increased in patients with chronic kidney failure and those undergoing hemodialysis and it has been thought that high leptin value may contribute to uremic anorexia and malnutrition." (PMID 28197429, 2012). "Subsequently, we examined the impact of malnutrition on adipocytokines in T2DM by measuring the plasma levels of adiponectin, adipsin, resistin, leptin and visfatin in LBMI and NBMI individuals." (PMID 33183277, 2020). "In the case of malnutrition, the lack of protective immunity can be easily traced back to the developmental defects associated with inadequate nutrients and the lack of nutritional signals such as leptin that are critical for fueling immune cell proliferation and function." (PMID 29868016, 2018). "Successful PTX was found to improve anemia and malnutrition in severe SHPT patients, and this was correlated with increased circulating leptin levels via up-regulated Akt signaling in adipocytes." (PMID 27307101, 2016). "All psychological conditions leading to malnutrition, such as anorexia nervosa, affect AAM due to low leptin levels that results in impaired secretion of GnRH." (PMID 25050345, 2014). "Accordingly, a low leptin level has often (but not always) been associated with a low BMI and a low MNA score in adults with malnutrition, as was the case in our study population." (PMID 35011102, 2022). "In addition, at the end of the experiment, we measured markers of malnutrition and stress, including IGF-1, leptin, corticosterone, and IgA levels." (PMID 34207946, 2021). "Another approach to this issue has been the study of Mtb infection in mice not expressing leptin, an adipokine reduced in malnutrition and fasting." (PMID 33936040, 2021). "Besides routine clinical and serum data at baseline and 12 months, Malnutrition Universal Screening Tool (MUST) score and serum concentration of leptin and adiponectin were measured for each participant at baseline." (PMID 33816531, 2021). "Hence, malnutrition is connected with higher levels of the HbA1c, RBG, pancreatic hormones, adiponectin and adipsin and lower levels of leptin in T2DM individuals." (PMID 33183277, 2020).
malnutrition (continued). "Near-total lack of fat in congenital/acquired generalized lipodystrophy, cachexia, or any other severe malnutrition condition induces severe multi-organ dysfunction due to lack of production of leptin and other adipokines." (PMID 32056035, 2020). "In this study, the fascinating outcome is the serum leptin levels significantly reduced by the parasite infection irrespective of malnutrition i.e., systemic leptin levels were reduced in well-nourished infected animals also." (PMID 29868503, 2018). "To follow up on our earlier report and to test if leptin administration could be protective in malnutrition coupled VL38, we investigated the effects of exogenous leptin in malnutrition coupled L. donovani infection in BALB/c mice." (PMID 29116252, 2017). "Second, among the several cytokines and adipokines we tested, only leptin differed between patients with and without malnutrition." (PMID 27583675, 2016). "In our study group, there were no obese persons and in 1/3 of patients the low serum leptin levels were indicative of malnutrition." (PMID 22518129, 2012). "It is worth noting that studies reporting malnutrition-related decreases in serum leptin concentration primarily focused on women, and may not be fully representative of the entire elderly population." (PMID 38622502, 2024). "In addition, hypoxia or periconceptional malnutrition modulate epigenetic processes such as DNA methylation in genes such as HIF in hypoxia and LEP, INSIGF, and GNASAs in periconceptional malnutrition, promoting metabolic or inflammatory processes that lead to obesity or diseases such as T2D." (PMID 36839169, 2023). "We first revealed that adipocytes produced more leptin through up-regulated Akt signaling because of normalization with high PTH environment, which in turn increased circulating leptin levels, and finally improved anemia and malnutrition in severe SHPT patients after PTX." (PMID 27307101, 2016). "Finally, a small sample size may have increased the probability of type II errors in hypothesis testing; despite this, we identified serum leptin and INR as robust markers of malnutrition in a well-phenotyped cohort of hospitalized cirrhotic patients." (PMID 27583675, 2016). "Since BMI and BFM values do not differ according to the sex and the presence or absence of cirrhosis, increased serum leptin levels could not be simply dedicated to BFM or malnutrition status in cirrhosis." (PMID 15387890, 2004). "Further, we noticed that within the same BMI range, patients who became malnourished at 12 months had relatively higher A/L ratio compared to those who did not, suggesting that the serum levels of adiponectin and leptin may play a role in predicting future malnutrition." (PMID 33816531, 2021).
psoriasis (108 papers, 2012 to 2025). An autoimmune condition characterized by red, well-delineated plaques with silvery scales that are usually on the extensor surfaces and scalp. "Obese patients with psoriasis had low adiponectin and high leptin levels that were positively associated with the severity of psoriasis." (PMID 40559401, 2025). "In an in vivo study, leptin deficiency attenuated imiquimod‐induced psoriasis‐like skin inflammation in a leptin‐deficient (ob/ob) mouse model." (PMID 37275420, 2023). "Leptin is associated with the promotion of pro-inflammatory cytokines and psoriasis-related cells, such as Th17." (PMID 37047363, 2023). "An increased production of T helper 1 and IL-17A cytokines, which play a central role in the pathogenesis of psoriasis, was associated with leptin." (PMID 37895330, 2023). "Coherently, murine models genetically deficient for leptin showed attenuation of psoriasis, while studies conducted on patients with psoriasis demonstrated higher levels of this hormone compared to healthy controls, even in nonobese subjects." (PMID 36012327, 2022). "Leptin-deficient (ob/ob) mice exhibited reduced skin inflammation in an IMQ-induced psoriasis model." (PMID 35457132, 2022). "Leptin as well as resistin, is involved in Foxp3 + regulatory T-cell (Treg) deficiency in psoriasis, which lead to chronic activation of effector and memory T cells." (PMID 33927259, 2021). "Adiponectin deficiency, leptin, visfatin and chemokine can induce and aggravate psoriasis by activating plasmacytoid dendritic cells and T cells." (PMID 34122426, 2021). "Recently, several studies revealed the roles of leptin in wound healing, the hair cycle, and the pathogenic development of skin diseases, such as psoriasis, lupus erythematosus, and dermatological cancers." (PMID 33597945, 2020). "Studies in psoriasis have shown that leptin levels are elevated in psoriatic patients compared with healthy controls, and psoriasis is an independent risk factor for hyperleptinemia." (PMID 27455297, 2016). "A rather popular polymorphism, G-2548A, located upstream from leptin gene coding region, has been studied for possible involvement in psoriasis." (PMID 24600521, 2014). "Leptin gene polymorphisms and their association with psoriasis have been given very little attention." (PMID 24600521, 2014). "Hyperleptinemia has been implicated in MS, and elevated leptin levels have also been reported in psoriasis, though their precise role remains unclear." (PMID 40909067, 2025). "This might be because the increase in BMI was associated with increased skin inflammation, elevated leptin, and reduced adiponectin, which was further linked with increased progression of psoriasis, thus leading to a lower treatment response to vunakizumab." (PMID 41567644, 2025). "The aim of this study was to evaluate the inflammatory potential and the association of psoriasis with metabolic and cardiovascular risk by analyzing serum concentrations of homocysteine, adiponectin, resistin, leptin, and pentraxin 3 in pediatric patients with psoriasis." (PMID 40095687, 2025). "Conversely, resistin and leptin, which were modestly upregulated in this study, are known to promote Th1 and Th17 immune responses and have been implicated in systemic inflammation and psoriasis severity." (PMID 39769200, 2024). "Leptin may be a marker of the severity of psoriasis, and may also be a pathogenic cofactor leading to chronic psoriasis." (PMID 37207234, 2023). "In humans, leptin has been associated with autoimmunity mainly because elevated leptin levels have been observed in rheumatoid arthritis, systemic lupus erythematosus, psoriasis, inflammatory bowel disease, and ITP." (PMID 34299256, 2021). "Therefore, in the case of diseases with underlying proinflammatory conditions which include psoriasis it is important to lower the level of expression of leptin and genes connected with it." (PMID 33562571, 2021).
psoriasis (continued). "Finally, there is still little attention paid to the leptin gene polymorphism in a course of psoriasis." (PMID 33008429, 2020). "On the other hand, since alterations caused by mutation of the LEPTIN gene have been less addressed, the focus of the current paragraph is to discuss the recent work describing the relationship between single nucleotide polymorphisms (SNPs) of the LEPTIN gene and the development of psoriasis." (PMID 33597945, 2020). "However, more large-scale clinical investigations are still needed to further elucidate the comprehensive relationship between diverse SNPs of LEPTIN gene and the risk and severity of psoriasis." (PMID 33597945, 2020). "Other adipocytokines apart from leptin and adiponectin may also be involved in the association between IR and psoriasis." (PMID 25977937, 2015). "It is also possible that the input of certain leptin gene variants in the pathogenesis of psoriasis may be limited." (PMID 24600521, 2014). "However, other studies have detected significant differences accompanied by similarly varying levels of leptin, thus indicating involvement of at least one leptin gene polymorphism in psoriasis." (PMID 24600521, 2014). "Considering all these adipokine level modifications in the setting of the inflammatory processes of psoriasis, we proceeded to study possible involvement of the gene encoding leptin in psoriasis, searching for a possible correlation between a gene polymorphism and the disease." (PMID 24600521, 2014). "Hyperleptinemia is associated with psoriasis and leptin acts as an angiogenic factor." (PMID 24600521, 2014). "In addition, elevated BMI and serum leptin levels were acknowledged as critical factors associated with delays in therapeutic responses, further positioning the negative role of systemic inflammation and metabolic imbalances in the management of psoriasis." (PMID 39767248, 2024). "Finally, leptin is likely implicated in the increased rates of psoriasis in obese individuals." (PMID 36766689, 2023). "The authors proposed that serum levels of leptin and the level of thickness of the carotid middle intima should be routinely evaluated, with the latter involving evaluating hyperlipidaemia, thus reducing the risk of morbidity and cardiovascular mortality and improving the prognosis of psoriasis." (PMID 31275060, 2019). "Adipose tissue has been identified not only as an active endocrine organ, but also an immune organ that produces varied immune cells and inflammatory-related cytokines such as TNF-α, leptin, and IL-6, which exacerbate the inflammatory processes in psoriasis." (PMID 40796893, 2025). "Leptin levels were significantly elevated in patients classified within the PSO–MS subgroup in comparison to those with psoriasis (PSO), with a statistically significant difference observed (p < 0.01)." (PMID 40003621, 2025). "Leptin: Mean (±SD) 5.6 (1.7) ng/mL in the psoriasis group vs. 3.2 (1.4) ng/mL in the control group (p < 0.001, two-tailed; effect size = 0.31)." (PMID 40095687, 2025). "Our findings demonstrated elevated leptin levels in pediatric psoriasis patients compared to controls, which corresponds to studies on adult populations." (PMID 40095687, 2025). "On the contrary, leptin, visfatin and resistin appear to be positively correlated with psoriasis activity." (PMID 40584532, 2025). "Leptin promotes the differentiation of Th1 and Th17 cells, which are central to autoimmune responses in both psoriasis and T1DM." (PMID 40277935, 2025). "Multiple studies have consistently demonstrated that serum leptin levels are significantly elevated in patients with psoriasis and positively correlate with disease severity." (PMID 40277935, 2025). "Leptin has been demonstrated to modulate DCs and helper T cells, key players in psoriasis immunopathogenesis." (PMID 41226468, 2025).
psoriasis (continued). "In this study, we observed elevated levels of inflammatory markers such as homocysteine, pentraxin 3, resistin, and leptin as well as a reduced levels of anti-inflammatory adiponectin in pediatric psoriasis patients compared to healthy controls." (PMID 40095687, 2025). "On the other hand, meta-analyses have shown that the circulating leptin levels are higher in individuals with psoriasis, correlating with disease severity." (PMID 38929716, 2024). "Adipose tissue acts as an endocrine organ, resulting in the formation of cytokines associated with both psoriasis and NAFLD (adipocytokines, adipokines (leptin and resistin) TNF-α, and IL-6)." (PMID 38473907, 2024). "Proinflammatory adipokines (TNF-α, IL-1, IL-6, and leptin) play a role in keratinocyte proliferation, and IL-1 is involved in molecular adhesion in the pathophysiology of psoriasis." (PMID 38473907, 2024). "Increased serum leptin concentration in patients indicates its significant role in the pathogenesis of psoriasis." (PMID 39063202, 2024). "Leptin increases the synthesis of pro-inflammatory mediators that play an important role in the development of psoriasis, such as TNF-α and CXCL8." (PMID 36675592, 2023). "Several studies on psoriasis patients reported high levels of leptin, which correlated with obesity and the severity of the disease." (PMID 37895330, 2023). "Skin biopsy samples examined by immunohistochemistry for leptin and leptin receptor expression revealed an elevated expression in patients with severe psoriasis." (PMID 37047363, 2023). "On the other hand, the ADIPOQ and LEP genes were found to play a notable role in the gene-to-gene interaction networks in the genomes of psoriasis patients." (PMID 36980866, 2023). "In the first step of our study, we compared the plasma concentrations of adiponectin, leptin, and resistin between patients with psoriasis and healthy control subjects." (PMID 36675592, 2023). "Previous studies have shown higher plasma leptin levels in psoriasis patients compared to healthy subjects." (PMID 36675592, 2023). "In our study, we found increased plasma concentrations of leptin and resistin in patients with psoriasis, while adiponectin levels were significantly lower than in healthy subjects." (PMID 36675592, 2023). "It’s observed that individuals suffering from psoriasis tend to showcase elevated leptin concentrations, with their serum levels being markedly higher in comparison to their healthy counterparts." (PMID 38035065, 2023). "The role of leptin in the pathogenesis of psoriasis has also been confirmed in numerous animal model studies." (PMID 36675592, 2023). "Studies also found that the serum leptin level in psoriasis patients was higher than that in healthy controls." (PMID 37207234, 2023). "Firstly, serum leptin and the expression of its receptor are elevated in severe psoriasis compared to mild disease and controls." (PMID 37047363, 2023). "Leptin has been shown to increase the synthesis of pro-inflammatory mediators involved in the pathogenesis of psoriasis, such as IL-1, IL-6, TNF-α, and CXCL8." (PMID 36675592, 2023). "The results of our study confirm the role of adiponectin, leptin, and resistin in the pathogenesis of psoriasis." (PMID 36675592, 2023). "Our study examined plasma concentrations of adiponectin, leptin, and resistin in patients with psoriasis." (PMID 36675592, 2023). "Adiponectin has been shown to have a protective effect on the development of psoriasis, while leptin and resistin exert pro-inflammatory effects." (PMID 36675592, 2023). "The concentrations of leptin and resistin were higher in patients with psoriasis than in the control group, while adiponectin concentrations were lower." (PMID 36675592, 2023). "Elevations in serum leptin are being used as a biomarker for both the diagnosis and severity of psoriasis." (PMID 35628271, 2022).